ENSG00000206977
Synonyms: LOC124900222
Gene: Small nucleolar RNA gene on chromosome 6 (41,832,854 to 41,832,993, forward strand). Ensembl gene ENSG00000206977.
Gene Ontology:
Biological process: RNA processing
Cellular component: nucleolus
Homologues: Orthologues: mouse Gm25791 (83% identical), mouse Gm26236 (82% identical), rat LOC120103270 (75% identical). Paralogues in human: SNORA8 (89% identical).